Y_RNA (Y RNA )
Gene: Miscellaneous RNA gene on chromosome X (41,316,488 to 41,316,589, forward strand). Ensembl gene ENSG00000238426.
Homologues: Orthologues: macaque Y_RNA (92% identical). Paralogues in human: Y_RNA (93% identical), Y_RNA (92% identical), RNY3 (91% identical), Y_RNA (91% identical), RNY3P1 (90% identical), Y_RNA (90% identical), RNY3P14 (89% identical), Y_RNA (89% identical), Y_RNA (88% identical), Y_RNA (87% identical), Y_RNA (86% identical), RNY3P11 (85% identical), and 98 more.